PRPF8 (pre-mRNA processing factor 8)
Diseases named in the same sentence as PRPF8 in open-access papers (continued):
Sharing a sentence is not in itself a finding about the gene and the disease.
cancer (continued). "Nonetheless, these findings suggest that human cells are highly sensitive to PRPF8 expression levels and function, with even minor deviations potentially resulting in significant cancer-related consequences." (PMID 40136404, 2025). "As the potential of PRPF8 in cancer treatment becomes increasingly apparent, targeted drug research focusing on PRPF8 has emerged as a key area of interest in cancer therapy." (PMID 40136404, 2025). "Future research focusing on the precise mechanisms of PRPF8 in tumorigenesis, coupled with the development of targeted therapeutic approaches, will provide a promising avenue for personalized cancer treatments." (PMID 40136404, 2025). "The PRPF8-dependent apoptosis pathway is believed to offer therapeutic benefits in various cancer types, particularly in tumors that exhibit resistance to conventional treatments such as chemotherapy or radiotherapy." (PMID 40136404, 2025). "As RNA splicing becomes an emerging anti-cancer target, pre-mRNA processing factor 8 (PRPF8) which is the core protein of splicing has been extensively studied in recent years." (PMID 32690086, 2020). "We confirmed known gene interactions of PRPF8 and GRIA1 in testis and brain cortex, and observed a novel interaction of FGFR2, in breast and prostate, modulated by cancer risk-variants." (PMID 30545302, 2018). "Among these, NR2C2 and PRPF8 were present in all five cancers." (PMID 39657701, 2024). "Our results indicate that PRPF8 is overexpressed in HCC and associated with increased tumor aggressiveness (patient survival, etc.), expression of HCC-related splice variants, and modulation of critical genes implicated in cancer-related pathways." (PMID 36609600, 2023). "Furthermore, recurrent somatic mutations or changes in the expression levels of a number of U5 snRNP proteins (PRPF6, PRPF8, EFTUD2, DDX23, and SNRNP40) have been associated with human cancers." (PMID 33584830, 2021). "Recent study reported that knockdown of PRPF8 significantly impairs mitophagosome formation, thus, these findings demonstrate that PRPF8 is essential for mitophagy and suggest that dysregulation of spliceosome-mediated mitophagy may contribute to pathogenesis of disease such as cancer." (PMID 32690086, 2020). "Therefore, further investigation into the widely applicable downstream targets activated by PRPF8 across different tumors or at various stages of tumor progression may enhance the understanding of cancer development mechanisms and offer promising implications for cancer therapy." (PMID 40136404, 2025). "We show that the presence of PRPF8 is instrumental for the inclusion (in other words, the reduced skipping) of FN1 exon 40.2, a cassette exon shown here to be more prevalent in tumor samples than in normal tissues in a wide variety of cancer types." (PMID 36609600, 2023). "The ABL1-I418T, PIK3CB-R231H, CHEK2:c.-4C > T, BRCA2-P3292L, ABL1-E459G, PRPF8-G1796R, PHF6-R274Q, WT1-R435X and ATM-C117Y variants were potentially important cancer variants which were not actionable." (PMID 35896598, 2022). "Namely, we speculate that therapeutic targeting of splicing factors, including PRPF8 or XAB2, has the potential to disrupt BRCA1 function in cancer cells, which is known to correlate with improved therapeutic response to clastogens." (PMID 29212152, 2017).
tumor (6 papers, 2020 to 2025). "It is essential to further investigate how specific mutations in PRPF8 affect AS in a context-dependent manner, particularly in relation to tumor type and stage." (PMID 40136404, 2025). "Tumor therapies targeting PRPF8 from various angles and multiple pathways are actively being researched and developed; however, the current body of research remains largely theoretical." (PMID 40136404, 2025). "Numerous studies have demonstrated that PRPF8 regulates AS of various genes, either directly or indirectly, across different tumors, thereby significantly influencing apoptosis in tumor cells." (PMID 40136404, 2025). "Specifically, in vivo silencing of PRPF8 by siPRPF8 in established s.c. tumors significantly reduced tumor growth and the final tumor weight compared to those of scramble-treated tumors." (PMID 36609600, 2023). "PRPF8 silencing ameliorated aggressiveness in vitro and decreased tumor growth in vivo." (PMID 36609600, 2023). "In addition, this study is the first to show that in vivo silencing of PRPF8 using a specific siRNA in growing Hep3B xenografts can significantly reduce tumor progression in this preclinical HCC model." (PMID 36609600, 2023). "The results demonstrated that EEF2, G3BP1, G3BP2, PRPF8, RECQL4, STOML2, and UBB exhibited significantly higher expression levels in the majority of tumor tissues, whereas METTL3 and NR2C2 showed a widespread downregulation trend." (PMID 41341921, 2025). "Specifically, the splicing machinery components KHDRBS1, NOVA1, PRPF8, SNW1, SRSF1, SRSF10 and SRSF9 were overexpressed in tumor tissue." (PMID 38049848, 2023). "To this end, since their expression was augmented in tumor tissue, we performed silencing experiments of NOVA1, PRPF8 and SRSF10 in UMC-11 and NCI-H727 cells, two distinct broadly used pulmonary carcinoid cell models." (PMID 38049848, 2023). "However, the regulatory factors reported in these studies are inconsistent, and downstream targets of PRPF8, such as PIRH2, RBMX, and APC2, exhibit low reproducibility across different tumor types." (PMID 40136404, 2025). "Interestingly, 16 of the 34 components examined (47.1%) were altered and, in line with our Discovery cohort, KHDRBS1, NOVA1, PRPF8, SNW1, SRSF1, and SRSF9 were also overexpressed in tumor tissue in this external cohort." (PMID 38049848, 2023).
infection (3 papers, 2022). The state of being infected such as from the introduction of a foreign agent such as serum, vaccine, antigenic substance or organism. "Surprisingly, T3DS infection led to a striking reduction in PRPF8 (80%) protein levels, and a more modest reduction in EFTUD2 (35%) and SNRNP200 (25%)." (PMID 35489070, 2022). "However, this raises an interesting question: if μ2 only blocks translation, how can it induce such a sharp decrease in PRPF8 (80%), as recently described, during the course of a 16 h infection?" (PMID 36614170, 2022). "μ2 impacts cellular AS by interacting with U5 snRNP proteins EFTUD2, PRPF8, and SNRNP200, and reducing their levels during infection." (PMID 36560714, 2022). "The structural protein μ2 appears to be the main determinant of these AS modifications by decreasing the levels of U5 core components EFTUD2, PRPF8, and SNRNP200 during infection." (PMID 36614170, 2022). "We previously demonstrated that MRV reduces the protein levels of EFTUD2, PRPF8, and SNRNP200 through the action of the μ2 protein during infection." (PMID 36560714, 2022). "The P208S mutation did not affect the reduction of either PRPF8 or SNRNP200, suggesting the P208S mutant retains its ability to reduce PRPF8 levels, as seen during T3DK infection." (PMID 35489070, 2022). "However, we did not observe any defect in cell proliferation by RTCA, any difference in cell death by FACS, nor any significant enhancement in Cas3/7 activity when silencing PRPF8 in the absence of infection." (PMID 36560714, 2022). "Surprisingly, PRPF8 KD led to a considerable amount of pMLKL in the absence of infection, revealing that the enhanced cell death observed with this KD could be attributable, at least in part, to necroptosis." (PMID 36560714, 2022). "Moreover, EFTUD2 and PRPF8 control the induction of the IFN response pathway, establishing the U5 snRNP as a potent target for viruses to abrogate the cellular response mounted against infection." (PMID 36560714, 2022). "We also validated that the depletion of EFTUD2, PRPF8, and SNRNP200 was not decreasing cell viability, and that cell survived and even expanded throughout the course of the experiment in the absence of infection." (PMID 36560714, 2022).
blood cancers (2 papers, 2021 to 2025). "In addition to blood cancers, mutations in the gene PRPF8 are also associated with NDDs." (PMID 40066647, 2025).
neurodevelopmental disorder (2 papers, 2025 to 2026). A behavioral and cognitive disorder with onset during the developmental period that involves impaired or aberrant development of intellectual, motor, or social functions. "A total of six de novo missense variants were located in genes previously identified as causal for a neurodevelopmental disorder, of which three variants in PRPF8, TRIO and ZBTB7A were classified as likely pathogenic." (PMID 40836029, 2026). "First report of a homozygous case of neurodevelopmental disorder associated with a novel PRPF8 variant." (PMID 40066647, 2025). "While recently identified heterozygous PRPF8 variants have been linked to various human diseases, their role in neurodevelopmental disorders (NDDs) remains ambiguous." (PMID 40066647, 2025). "Replication in a person who stutters is required to confirm that stuttering is a feature of the monogenic neurodevelopmental disorders associated with mutations in SPTBN1, PRPF8, TRIO, and ZBTB7A, and to causally link FLT3 and IREB2 to neurodevelopmental disorders." (PMID 40836029, 2026). "While the authors acknowledge that some PRPF8 mutations might need further investigation, the evidence clearly pointed to PRPF8 playing an etiologic role in neurodevelopmental disorders." (PMID 40066647, 2025). "Exome sequencing analysis yielded a pathogenic variant in SPTBN1 as well as likely pathogenic variants in PRPF8, TRIO, and ZBTB7A - four genes previously implicated in neurodevelopmental disorders with or without speech problems." (PMID 40836029, 2026). "According to prior literature on the genes implicated by our de novo analyses, none of the patients with neurodevelopmental disorders caused by mutations in SPTBN1, PRPF8, TRIO, and ZBTB7A have been described to stutter." (PMID 40836029, 2026).
genetic diseases (1 paper, 2015). "Our findings exemplify the regulatory potential of changes in the core spliceosome machinery, which may be relevant to slow-onset human genetic diseases linked to PRPF8 deficiency." (PMID 26392272, 2015). "Mutations in human PRPF8 that disrupt these interactions, affecting spliceosome assembly and function, are found in autosomal dominant retinitis pigmentosa, a variable-onset hereditary disease that results in a progressively decreasing field of vision due to degeneration of rods and cones." (PMID 26392272, 2015).
psychiatric diseases (1 paper, 2024). "So far, there is no relevant research on CCT2, EPRS, and PRPF8 in psychiatric diseases." (PMID 38664915, 2024).
PRPF8 also shares sentences with these, for which no sentence is quoted: acute myeloid leukemia (2 papers); colon cancer (2); intellectual disabilities (2); Leber congenital amaurosis (2); Stroke (2); acrofacial dysostosis (1); Burn-McKeown syndrome (1); cerebellar degeneration (1); cerebrocostomandibular syndrome (1); Developmental delay (1); gyrate atrophy (1); Hyperinsulinemia (1); hypogonadism (1); ischemic stroke (1); mandibulofacial dysostosis Guion-Almeida type (1); metastatic cancer (1); metastatic disease (1); microcephaly (1); myeloproliferative neoplasm (1); Nager syndrome (1); nervous system disorder (1); neuroblastoma (1); pancreatic cancer (1); PRLomas (1); renal fibrosis (1); retinitis pigmentosa 1 (1); syndromic (1).